CADM1 (cell adhesion molecule 1)
Diseases named in the same sentence as CADM1 in open-access papers (continued):
Sharing a sentence is not in itself a finding about the gene and the disease.
idiopathic pulmonary fibrosis (3 papers, 2013 to 2022). Idiopathic pulmonary fibrosis (IPF) is a nonneoplastic pulmonary disease that is characterized by the formation of scar tissue within the lungs in the absence of any known cause. "This suggests that CADM1 may be a key molecule regulating the HLMC-HLF cross-talk which is believed to be important in the progression of idiopathic pulmonary fibrosis, and as such may prove to be an interesting therapeutic target." (PMID 23620770, 2013). "CADM1 is a key adhesion receptor regulating the adhesion of human lung mast cell (HLMC) with primary human lung fibroblast and human airway smooth muscle cell, which is believed to be important in the progression of idiopathic pulmonary fibrosis." (PMID 35334492, 2022).
Kaposi's sarcoma (3 papers, 2021 to 2023). A malignant neoplasm characterized by a vascular proliferation which usually contains blunt endothelial cells. "In the context of virus-infected cells, CADM1 expression has been shown to be upregulated upon Kaposi sarcoma-associated herpes virus (KSHV) infection of primary B cells and in human T-lymphotropic virus type 1 (HTLV-1)-infected cells." (PMID 36270981, 2022). "Similarly, in diseases, such as Kaposi’s sarcoma (KS) and primary exudative lymphoma (PEL) caused by Kaposi’s sarcoma herpes virus/human herpes virus 8 (KSHV/HHV8), CADM1 is possibly involved in chronic NF-κB activation." (PMID 34395444, 2021).
lymph node metastasis (3 papers, 2014 to 2022). "In addition, 43 matched pairs of primary tumors and lymph node metastasis samples (TMA III) were analyzed for CADM1 protein expression." (PMID 24833255, 2014).
meningioma (3 papers, 2016 to 2020). A generally slow growing tumor attached to the dura mater. "Interestingly, among genes enriched in the “cell adhesion molecules (CAMs)” pathway was cell adhesion molecule 1 (CADM1), whose loss of protein expression has formerly been found to correlate with increasing meningioma grade and reduced patient survival." (PMID 33167358, 2020).
Merkel cell carcinoma (3 papers, 2020 to 2023). "On the contrary to cutaneous lymphomas, CADM1 contributes to the favorable clinical behavior in solid tumors, except for in Merkel cell carcinoma." (PMID 33419290, 2020). "The higher CADM1 expression in Merkel cell carcinoma is significantly correlated with the decreased overall survival, and one case has been identified where CADM1 is associated with hypermethylation of the promoter region." (PMID 33419290, 2020).
mycosis fungoides (3 papers, 2020 to 2023). Classical mycosis fungoides is the most common type of mycosis fungoides (MF), a form of cutaneous T-cell lymphoma, and is characterized by slow progression from patches to more infiltrated plaques and eventually to tumors. "They investigated CADM1 expression in mycosis fungoides tumor cells to identify its utility as a diagnostic marker for mycosis fungoides." (PMID 33419290, 2020). "Regarding the contribution of CADM1 on the pathogenesis of mycosis fungoides, our study has revealed that the survival rate in mycosis fungoides is significantly lower in patients with high CADM1-expressed groups." (PMID 33419290, 2020). "In addition, another study has revealed a more precise and detailed analysis of the contribution of CADM1 on mycosis fungoides." (PMID 33419290, 2020). "Therefore, CADM1 expression in mycosis fungoid tumor cells is negatively related to the prognosis of mycosis fungoides." (PMID 33419290, 2020).
Sézary Syndrome (3 papers, 2020 to 2023). "Sézary syndrome (SS) patients with high frequency of peripheral CADM1+ cells show an unfavorable clinical behavior." (PMID 33419290, 2020). "Only one study has reported the involvement of CADM1 in Sézary syndrome, however, their analyses suggest to us an important insight of CADM1 roles in cutaneous lymphoma." (PMID 33419290, 2020). "In their Sézary syndrome patient series analysis, CADM1 was expressed in patients with progressive type Sézary syndrome." (PMID 33419290, 2020).
T-cell lymphoma (3 papers, 2019 to 2023). "For HTLV-1-associated T cell lymphomas and KSHV-associated primary effusion lymphoma, CADM1 has been described to support viral oncogene-driven NF-κB activation, and thereby to directly drive transformed lymphocyte proliferation." (PMID 36270981, 2022). "In addition, CADM1 mediates cytotoxic lymphocyte recognition of tumor cells, including HTLV-1-associated CD4+ T cell lymphomas." (PMID 36270981, 2022). "In the first of their studies published in close succession, tumors from 117 Cadm1−/−; SB and 73 Cadm1+/+; SB littermates were found to be predominantly CD3-positive T-cell lymphoma." (PMID 31338332, 2019).
acute lymphoblastic leukemia (2 papers, 2019 to 2022). Leukemia with an acute onset, characterized by the presence of lymphoblasts in the bone marrow and the peripheral blood. "Accordingly, CADM1 is frequently silenced in acute lymphoblastic leukemias." (PMID 36270981, 2022). "Another study showed that Tax expression in the T-cell acute lymphoblastic leukemia (T-ALL) CEM cell line does not induce CADM1 expression, but it highly activates CADM1 expression in combination with the phorbol 12-myristate 13-acetate (PMA)/calcimycin (CAI) treatment through T-cell activation." (PMID 30837480, 2019).
acute monoblastic leukaemia (2 papers, 2014 to 2020). "Interestingly, high levels CADM1 in mixed-lineage leukaemia-rearranged acute monoblastic leukaemia provide better overall survival." (PMID 24465823, 2014).
allergic disease (2 papers, 2012 to 2015). An immune response that occurs following re-exposure to an innocuous antigen, and that requires the presence of existing antibodies against that antigen. "Recent studies have revealed that alterations in the transcriptional or post-transcriptional expressions of CADM1 correlate with the pathogenesis of pulmonary diseases and allergic diseases." (PMID 26636084, 2015). "CADM1 may also contribute to the longevity of MCs and, thereby, augment pathology of disorders such as asthma and allergy." (PMID 22438059, 2012).
atherosclerosis (2 papers, 2019 to 2023). A disease characterized by the build-up of fatty material and calcium deposition in the arterial wall resulting in partial or complete occlusion of the arterial lumen. "Cell adhesion molecule-1 (CAM-1) is very common in human atherosclerotic plaques and can be regulated by various stimuli, suggesting that ICAM-1 plays a role in atherosclerosis." (PMID 30838022, 2019). "Prior studies have reported that some components of the MedDiet such as nuts may downregulate inflammatory markers related to atherosclerosis, such as serum C-reactive protein (CRP), interleukin 6 (IL-6), cell adhesion molecule-1 (CAM-1), and intercellular adhesion molecule-1 (ICAM-1)." (PMID 35192097, 2023).
bone cancer (2 papers, 2022 to 2025). A primary or metastatic malignant neoplasm affecting the bone or articular cartilage. "For example, the cell adhesion molecule 1 (CADM1) gene in bone cancer works by sponging miRNA, opening the way for the development of novel therapeutics." (PMID 35886037, 2022).
breast invasive carcinoma (2 papers, 2012 to 2022). "The down-regulation of Cadm1 in invasive breast cancer, primarily by promoter hypermethylation, has been reported in at least four studies." (PMID 23028344, 2012).
breast tumor (2 papers, 2012 to 2014). "CADM1 protein expression could be assessed in a large number of primary breast tumors (TMA I, n= 1331) and 27 BCBM samples." (PMID 24833255, 2014). "Clinico-pathologic examination of both independent patient cohorts consisting of 1718 primary breast tumor samples revealed a significant association between negative CADM1 status and advanced tumor stage, positive lymph node status and larger tumor size (all p < 0.05)." (PMID 24833255, 2014).
chronic kidney disease (2 papers, 2018 to 2020). Impairment of the renal function secondary to chronic kidney damage persisting for three or more months. "The decreased CADM1 expression causes apoptosis of renal tubular epithelial cells and promotes renal tubulointerstitial and tubular injuries, resulting in the development of chronic kidney disease." (PMID 33419290, 2020). "A total of 44 patients (35%) had elevated serum CADM1 concentration in chronic kidney disease, suggesting that CADM1 is a marker for evaluating the damage in tubulointerstitial tissues in chronic kidney disease." (PMID 33419290, 2020). "CADM1 is also reported to be a possible biomarker for chronic kidney disease." (PMID 33419290, 2020). "By conducting the in vitro studies, it may be found that CADM1 ectodomain shedding could contribute to the development of chronic kidney disease (CKD)." (PMID 30460232, 2018).
Diabetes (2 papers, 2022 to 2023). "Interestingly, the number of Cadm1+ macrophages was lowest at age 15 weeks, which generally coincides with the manifestation of hyperglycemia in NOD mice and can indicate that Cadm1 function in intercellular binding may be relevant to diabetes pathogenesis around the age of 8 weeks in these animals." (PMID 35133983, 2022). "In summary, the precise function of CADM1 in myeloid cells present in the islet microenvironment during diabetes pathogenesis had not been studied before, to our knowledge, and here we report its identification as a mediator of immune cell interactions in this context." (PMID 35133983, 2022). "Immunostaining of human pancreata revealed an increased number of CADM1+glucagon+ cells adjacent to CD8+ T cells in sections from T1D and aAb+ donors compared with individuals without diabetes." (PMID 35133983, 2022). "Numbers of CADM1+CD68+ peri-islet myeloid cells adjacent to CD8+ T cells were also increased in pancreatic sections from both T1D and aAb+ donors compared with individuals without diabetes." (PMID 35133983, 2022). "We show that numbers of CADM1+ islet endocrine and myeloid cells adjacent to CD8+ T cells are increased in pancreatic sections from individuals with T1D and those who are autoantibody-positive (aAb+), compared with individuals who do not have diabetes (Non)." (PMID 35133983, 2022).
Hyperglycemia (2 papers, 2014 to 2022). An increased concentration of glucose in the blood. "These lines of evidence suggest that CADM1 ectodomain shedding may be in an elevated state via PKC activation due to chronic hyperglycemia in T2DM." (PMID 24964098, 2014).
inflammatory bowel disease (2 papers, 2024 to 2026). A spectrum of small and large bowel inflammatory diseases of unknown etiology. "By silencing CADM1 in rats with inflammatory bowel disease, Sun and colleagues demonstrated that CADM1 can improve intestinal barrier function." (PMID 38895122, 2024).
malignant pleural mesothelioma (2 papers, 2021 to 2022). A malignant neoplasm that arises from mesothelial cells in the pleura and shows a diffuse growth pattern. "Moreover, CADM1 expression in malignant pleural mesothelioma appeared to be associated with efficient adhesion and growth on CADM1 expressing mesothelium." (PMID 34257559, 2021).
metastasis (2 papers, 2014 to 2016). The spread or migration of cancer cells from one part of the body (where they first appeared) to another. "CADM1 plays a role in cell–cell adhesion and reduced expression of this gene is correlated with lymph node metastasis." (PMID 25065733, 2014).
oral squamous cell carcinoma (2 papers, 2020 to 2024). "CADM1 promoter methylation is associated with unfavorable survival rates in patients with oral squamous cell carcinoma." (PMID 33419290, 2020).
osteoporosis (2 papers, 2012 to 2023). A condition of reduced bone mass, with decreased cortical thickness and a decrease in the number and size of the trabeculae of cancellous bone (but normal chemical composition), resulting in increased fracture incidence. "Postmenopausal osteoporosis is characterized by weak but flexible bone with low mineral content and three of the identified knockout strains (Bbx, Cadm1, Fam73B) had phenotypes in this category." (PMID 22876197, 2012).
primary effusion lymphoma (2 papers, 2018 to 2022). A large B-cell lymphoma located in the body cavities, characterized by pleural, peritoneal, and pericardial fluid lymphomatous effusions and that is always associated with human herpes virus-8 (HHV-8). "We next determined if CADM1 mRNA and protein expression were upregulated in primary effusion lymphoma (PEL) cell lines (BC-1, BC-3, BCBL-1, and UM-PEL-3) that are latently infected with KSHV." (PMID 29698475, 2018).
tropical spastic paraparesis (2 papers, 2016 to 2020). "Peripheral blood mononuclear cells from ATL patients, asymptomatic HTLV-1 carriers and patients with HTLV-1 associated myelopathy/tropical spastic paraparesis (HAM/TSP) were stained with a panel of antibodies specific for 24 TCRVβ subunits and CADM1." (PMID 27893842, 2016). "PBMCs from healthy volunteers; ACs; and patients with smoldering-, chronic-, acute-type ATL, and HAM/TSP (HTLV-1-associated myelopathy/tropical spastic paraparesis) were analyzed with flow cytometry, using PpIX and TSLC1/CADM1 (tumor suppressor in lung cancer 1/cell adhesion molecule 1) parameters." (PMID 32024297, 2020).
Venous thrombosis (2 papers, 2013 to 2024). Formation of a blood clot (thrombus) inside a vein, causing the obstruction of blood flow. "It is essential for human health, since modulation of expression, SNPs or mutations in CADM1 have been implicated in several diseases including cancer, autism spectrum disorder and venous thrombosis." (PMID 23063768, 2013). "Since CADM1 is a tumour suppressor in several cell types, this may predispose to various cancers and other diseases in which CADM1 is implicated, such as venous thrombosis." (PMID 23063768, 2013). "CADM1 protein expression has also been demonstrated in endothelial and smooth muscle cells throughout the human macro- and microvascular systems, and single-nucleotide polymorphisms in regulatory and intronic regions of the CADM1 gene have been associated with risk of venous thrombosis." (PMID 39356664, 2024). "CADM1 expression is also reduced in endothelial cells in venous thrombosis." (PMID 23063768, 2013).
acute T cell leukaemia (1 paper, 2012). "In contrast, CADM1 is upregulated in acute T cell leukaemia and contributes to tissue infiltration." (PMID 22438059, 2012). "For example, the CADM1 partners, TIAM in acute T cell leukaemia or PTPN13 in epithelial cells, are not expressed in MCs." (PMID 22438059, 2012).
alcohol abuse (1 paper, 2014). The use of alcoholic beverages to excess, either on individual occasions ("binge drinking") or as a regular practice. "Hypermethylation of CADM1 was associated with higher age (P = 0.050), no history of alcohol abuse (P = 0.007), or smoking (P < 0.001)." (PMID 25065733, 2014).
amyloidosis (1 paper, 2024). A disorder characterized by the localized or diffuse accumulation of amyloid protein in various anatomic sites. "Additional astrocyte hub genes in the ETC, including NRXN1, CADM1, MACF1, MAGI2, LRP4, GJA1 and ADGRL3, have been identified as markers of a reactive astrocyte state, implicating them in amyloidosis, regulation of neuroinflammation, cellular interactions." (PMID 38913039, 2024).
angiosarcoma (1 paper, 2020). A malignant tumor arising from the endothelial cells of the blood vessels. "Furthermore, the role of CADM1 on other cutaneous malignancies, such as basal cell carcinoma, solar keratosis, and soft tissue malignant tumors, especially angiosarcoma, has not yet been elucidated." (PMID 33419290, 2020).
B cell lymphomas (1 paper, 2022). "Both cell intrinsic and extrinsic effects of CADM1 in the respective T and B cell lymphomas have been described." (PMID 36270981, 2022).
Cachexia (1 paper, 2019). Severe weight loss, wasting of muscle, loss of appetite, and general debility related to a chronic disease. "Based on the fact that circulating levels of tumor-derived factors were correlated with cachexia development and predicted outcome in cancer, we also investigated the predictive potential of seven transcripts (NCAM1, CNTN1, SCG2, CADM1, IL-8, NPTX1, and APOD)." (PMID 31455042, 2019).
cardiomyopathy (1 paper, 2025). A disease of the heart muscle or myocardium proper. "lncRNA MCM3AP-AS1 alleviates sepsis-induced cardiomyopathy by improving inflammation, oxidative stress, and mitochondrial function through the inhibition of the miR-501-3p/CADM1/STAT3 axis." (PMID 40041174, 2025).
cervical adenocarcinoma (1 paper, 2020). An adenocarcinoma arising from the cervical epithelium. "MiRNA-mRNA interactions by miranda and targetscan analysis showed that the downregulated expression of CADM1, SBSPON, and FAM229B in cervical adenocarcinoma samples might be the potential target genes for miR-192-5p." (PMID 33024199, 2020).
cholangitis (1 paper, 2016). An acute or chronic inflammatory process affecting the biliary tract. "In cholangitis, miR-221 regulates the secretion of cell adhesion molecule 1 induced by interferon gamma in bile duct cells." (PMID 26901347, 2016).
colitis (1 paper, 2026). Inflammation of the colon. "Here, we investigated the role of CADM1 in IBD using a murine model of colitis induced by dextran sulfate sodium in both wild-type and conventional Cadm1-deficient (Cadm1-/-) mice." (PMID 42123493, 2026). "Cadm1-/- mice exhibited more severe colitis than wild-type mice with increased mortality (64% vs. 10%) and delayed recovery." (PMID 42123493, 2026).
colorectal adenocarcinoma (1 paper, 2014). The most common type of colorectal carcinoma. "CADM1 is known to interact specifically with the hemidesmosomal alpha6beta4 integrin, but not alpha5beta1 or alpha6beta1 integrins, in colorectal adenocarcinoma Caco-2 cells." (PMID 24465823, 2014).
ductal carcinomas (1 paper, 2014). "Loss of CADM1 was significantly associated with worse patient outcome among ductal carcinomas (p = 0.001 and p = 0.001), whereas a significant association was found for lobular carcinomas only in TMA II (p = 0.026; TMA I p = 0.068) (data not shown)." (PMID 24833255, 2014).
Fanconi anaemia (1 paper, 2021). "Among these, there were FHIT, WWOX, FANCC (belonging to the Fanconi anaemia pathway), CADM1, and IMMP2L." (PMID 34187875, 2021).
glomerulonephritis (1 paper, 2019). A renal disorder characterized by damage in the glomeruli. "Urinary CADM1 concentrations in patients with CKD based on various forms of glomerulonephritis and nephropathy (n = 127) were measured." (PMID 31316980, 2019).
hearing loss (1 paper, 2023). "Among the genes identified via FST and XP-EHH analyses, four are actually associated with hearing loss: CADM1, ESRRB, AKT3, and ATP2B2." (PMID 37570247, 2023).
Hypertension (1 paper, 2023). The presence of chronic increased pressure in the systemic arterial system. "Somatic mutations of CADM1 cause reversible hypertension and reveal a role for GJ communication in suppressing physiological aldosterone production." (PMID 37291193, 2023).
Infertility (1 paper, 2016). "The relevance of these proteins to fertility is indicated by mammalian phenotypes, including the role of Arsa as an acrosome vesicle zona pellucida binding protein and sperm maturation defects and infertility in Cadm1 mutants." (PMID 27804984, 2016).